CGAS (cyclic GMP-AMP synthase)
Diseases named in the same sentence as CGAS in open-access papers (continued):
Sharing a sentence is not in itself a finding about the gene and the disease.
breast carcinoma (continued). "qPCR analysis confirmed the upregulation of BRCA1, cGAS, STING, SEI1, and PD‐L1 expressions in the breast cancer cell lines or lymphoma cell lines treated with melphalan or bortezomib." (PMID 40135791, 2025). "Experiments using breast cancer patient-derived xenografts revealed that paclitaxel treatment activates type I IFN and TNFα and that a cGAS-STING-dependent apoptotic effect is required for the paclitaxel response in vivo." (PMID 41299712, 2025). "The cGAS-STING signaling pathway stands as a central orchestrator of innate and adaptive antitumor immunity within the breast cancer microenvironment." (PMID 41573551, 2025). "In particular, modulating the cGAS-STING pathway to overcome immune suppression and drug resistance will be an important direction for breast cancer immunotherapy." (PMID 40567603, 2025). "Combined with our findings that hyperactivated AKT1 blocked cGAS‐STING signaling, we proposed that inactivated STING signaling and hyperactivated AKT1 formed a positive feedback loop in endocrine‐resistant breast cancer." (PMID 39023171, 2024). "Several studies have demonstrated that the activation of the cGAS-STING pathway promotes DC maturation and induces cytotoxic lymphocytes’ infiltration in breast cancer." (PMID 38970078, 2024). "In summary, analysis of our own TMA and publicly available data showed that cGAS-STING inflammatory signaling was correlated with higher immune cell infiltration and better response to immune checkpoint inhibitor treatment in breast cancer patients." (PMID 38167507, 2024). "Briefly, we demonstrated that paclitaxel treatment triggers a proapoptotic secretome, dependent on the cGAS/STING pathway, in multiple breast cancer cell lines and patient-derived breast cancer cells." (PMID 38506114, 2024). "We analyzed the expression of key components of the cGAS-STING signaling pathway and their relation to replication stress markers, replication stress-inducing oncogenes, and immune cell markers in breast cancer patients." (PMID 38167507, 2024). "Here, we uncover that positive feedback loop of inactivated cGAS‐STING pathway and hyperactivated AKT1 is a crucial determinant of endocrine resistance in breast cancer." (PMID 39023171, 2024). "Both in vitro and in vivo results demonstrate that ZIF‐8@MnO2 effectively promotes the cGAS‐STING pathway and synergizes with PD‐L1 checkpoint blockades, leading to remarkable regression of local tumors as well as distant metastases of breast cancer." (PMID 38225693, 2024). "The EZH2-HMGA1-USP7 complex regulates the formation of CCF, and CCF activates cGAS, but USP7 is required to de-ubiquitinate cGAS and stabilize cGAS, EZH2 can promote breast cancer metastasis through cGAS-STING pathway activated by CCF." (PMID 38312740, 2024). "In the context of breast cancer, CIN and the subsequent DNA damage occur frequently and are known to activate cGAS-STING signaling." (PMID 38203626, 2023). "In particular, a study already has found that the formation of CCF in breast cancer cells is correlated to the overexpression of EZH2 and promotes breast cancer metastasis through the secretion of inflammatory factors by the cGAS-STING pathway." (PMID 37543653, 2023). "This review focuses on the cGAS-STING pathway and its current implications in DNA repair, the tumour microenvironment (TME), and mitochondrial function in breast cancer." (PMID 37448962, 2023). "Our results show that activated cGAS can be colocalized with the deubiquitinase USP7 in breast cancer cells, and USP7 can stabilize activated cGAS in the cGAS–STING pathway by affecting the ubiquitination of cGAS." (PMID 35163710, 2022). "Because CCF can activate cGAS, we next investigated if EZH2 can promote breast cancer cell migration and invasion through CCF." (PMID 35163710, 2022). "The purpose of this study is the mechanism of CCF formation and the activation of the cGAS-STING pathway, which will help people develop a new strategy for breast cancer." (PMID 35163710, 2022).
breast carcinoma (continued). "In lung and breast cancer cells, long-term induced inactivation of BRCA2 leads to upregulation of interferon-stimulated genes and activation of the cGAS/STING/STAT pathway, confirming that inactivation of BRCA2 triggers cellular innate immune responses." (PMID 34722771, 2021). "The effects of cGAS or SQSTM1 expression on cell growth and survival of breast cancer cells were also clarified through silencing of either cGAS or SQSTM1 in the MCF-7, MDA-231 and BT-549 cells." (PMID 34123836, 2021). "Hypoxia induces Tet1-dependent expression of miR-25/93 that targets NCOA3, a lysine acetyltransferase that epigenetically induces cGAS expression in cooperation with AP1, resulting in suppression of cGAS expression in hypoxic breast cancers." (PMID 29202128, 2017). "Furthermore, PCK1 S151 phosphorylation is negatively correlated with cGAS-STING activation and patient survival rates in human breast cancer specimens." (PMID 40567603, 2025). "Moreover, the link between cGAS-STING activation and genetic instability in breast cancer opens new avenues for personalized treatment strategies tailored to specific genetic backgrounds." (PMID 40567603, 2025). "In endocrine-resistant ER+HER2- breast cancer, while hyperactivated AKT1 suppresses cGAS-STING signaling by binding to TBK1 and disrupting the TBK1/STING/IRF3 complex, combining AKT1 inhibitors with STING agonists restores innate immune activation and impairs tumor growth in preclinical models." (PMID 41573551, 2025). "Coactivation of NF-κB and cGAS-STING pathways induced robust DC maturation, TAM reprogramming, and cytotoxic T cell infiltration, suppressing primary tumor growth and recurrence in 4T1 breast cancer models." (PMID 40846966, 2025). "Notably, ZMYND8 is overexpressed in breast cancer, where it promotes metastasis through dysregulation of HIF signaling, the cGAS-STING pathway, and cholesterol metabolism." (PMID 41297414, 2025). "Finally, we present a forward-looking perspective on the rational development of next-generation immunotherapies centered on cGAS-STING pathway modulation, outlining key priorities for achieving its full therapeutic potential in breast cancer." (PMID 41573551, 2025). "The cGAS-STING pathway, linking DNA damage to immune responses, plays a dual role in breast cancer." (PMID 40567603, 2025). "However, cGAS-STING scores were significantly higher in TNBCs, basal-like and HER2-enriched breast cancer subtypes, both in the TCGA (P < 0.001) and METABRIC cohorts (P < 0.001)." (PMID 38167507, 2024). "However, chronic cGAS/STING activation was shown to promote breast cancer metastasis in mice implanted with the MDA-MB-231 and 4T1 breast cancer cell lines." (PMID 38506114, 2024). "The cGAS-STING signaling is a key regulator in immune responses and plays a vital role in BRCA development and progression, but little is known about the role of cGAS-STING-related genes (CSRGs) in the clinical pathogenesis of breast cancer." (PMID 37051596, 2023). "Further evidence found that the cGAS-STING pathway induces inflammatory response through IL-6, IL-6R and STAT3, and induces CD8+T cell infiltration to enhance anti-tumor immune responses in breast cancer." (PMID 37051596, 2023). "Persistent activation of cGAS-STING signaling has been observed in different tumor types with high levels of CIN, including breast cancer, resulting in tumor progression, invasion, and metastasis formation through both cell-intrinsic and cell extrinsic mechanisms." (PMID 38203626, 2023). "As an endogenous member of the cGAS-STING signalling pathway, cGAMP exhibits significant potential as a STING agonist in anti-tumour therapy, as CAR-T cells generated using cGAMP display enhanced anti-tumour capacity in breast cancer." (PMID 37448962, 2023).
breast carcinoma (continued). "In vivo tumour growth of the chromosomally instable murine 4T1 breast cancer cells was clearly reduced when lacking cGAS or STING, indicating that STING activation in the context of CIN is not onco-protective per se." (PMID 36612027, 2022). "We find that KDM5 inhibition in luminal breast cancer cells results in R-loop-mediated DNA damage, reduced cell fitness, and an increase in ISG and AP signatures as well as cell surface major histocompatibility complex (MHC) class I, mediated by RNA:DNA hybrid activation of the CGAS/STING pathway." (PMID 41081756, 2025). "In the pathogenesis of breast cancer, the activation of the cGAS-STING signaling pathway plays a crucial role in enhancing antitumor immune responses, thereby suppressing the progression and metastasis of breast cancer, offering new potential strategies for immunotherapy in breast cancer." (PMID 40567603, 2025). "The article delves into the intricate interplay between the activation status of the cGAS-STING pathway and the tumor immune microenvironment across distinct breast cancer subtypes, elucidating how these interactions may lead to divergent clinical outcomes—either beneficial or detrimental." (PMID 40567603, 2025). "Indeed, cGAS-STING pathway induction was shown to be crucial for reprograming M2-like pro-tumoral macrophages into an M1-like anti-tumoral state in BMDMs and in ex vivo TAMs from colorectal and breast cancer." (PMID 38389103, 2024). "Thus, we examined whether PARP/HDACi can induce the accumulation of cytosolic DNA, which could activate the cGAS–STING signaling pathway and induce the transcription of type I IFNs in breast cancer cells." (PMID 38182579, 2024). "TNBCs have the strongest tumor immunogenicity among all breast cancer subtypes, and immunotherapies targeting PD-1 and PD-L1 have shown efficacy, 28 but therapies targeting cGas/STING are not yet practical and the efficacy of TNBCs as therapeutic targets is still unclear." (PMID 38106033, 2023). "We obtained 1087 breast cancer samples and 179 normal breast tissue samples from the Cancer Genome Atlas (TCGA) and Genotype-Tissue Expression (GTEX) database, 35 immune-related differentially expression genes (DEGs) from cGAS-STING-related genes were systematically assessed." (PMID 37051596, 2023). "The rapid and strong activation of the cGAS/STING pathway is reported to induce cytotoxic acute responses after DNA damage, but its chronic and constitutive activation offers a pro-survival space for chromosomally instable cancer cells, such as the acquired resistant breast cancer cells." (PMID 37242532, 2023). "For example, a study in breast cancer cells identified that part of the intracellular STING pool resides at the inner nuclear membrane, acting as a positive regulator of the DDR and shielding against excessive genomic instability separately from both cGAS and downstream interferon signalling." (PMID 36876871, 2023). "In addition, when breast cancer model cells were irradiated with therapeutic radiation, the EVs released from these breast cancer cells were taken up by dendritic cells, and then, they activated the cyclic GMP-AMP synthase (cGAS) within the dendritic cells." (PMID 36497144, 2022). "Cytoplasmic chromatin fragments (CCF) are recognized by the cytoplasmic DNA sensor cyclic GMP-AMP synthase (cGAS), which activates the cGAS–STING (cyclic GMP-AMP synthase-stimulator of interferon genes) pathway and promotes the production of inflammatory factors and breast cancer metastasis." (PMID 35163710, 2022). "Taken together, these data indicated that DNA autophagy in breast cancer cells could be selective autophagy of cytoplasmic free DNA but not nucleophagy and possibly involved cGAS, SQSTM1 and LC3." (PMID 34123836, 2021).
breast carcinoma (continued). "It has been demonstrated in breast cancer and NSCLC that treatment with PARP inhibitors enhances expression of PD-L1 by increasing cytosolic DNA and consequently activating the cyclic GMP-AMP synthase (CGAS)/stimulator of interferon genes (STING) innate immune signaling." (PMID 36046087, 2021). "For example, the breast cancer cell line MDA-MB-231 has a functional cGAS-STING axis, but pathway activation does not yield a type I IFN response or any other immune signaling, which suggests that cancer cells have inactivated the signaling route more downstream." (PMID 31658669, 2019). "Furthermore, the cGAS-Sting pathway was not activated in the metastatic cancer cells used in this study, suggesting that the mechanism of immune response in breast cancer is different from the mechanism proposed for Aicardi-Goutières Syndrome, a rare interferonopathy caused by RNase H2 mutation." (PMID 31125342, 2019). "In HER2+ breast carcinoma, it has been demonstrated that HER2 (unlike EGFR) suppresses cGAS-STING signaling, hindering the cancer cells from producing cytokines, entering senescence, and undergoing apoptosis." (PMID 38139802, 2023). "In breast cancer, elevated HMMR activates AURKA and reduces ARPC2 localisation in the mitotic cell cortex, which correlates with micronucleation and the activation of cGAS-STING and non-canonical NF-κB signalling." (PMID 38633247, 2024). "However, in endocrine‐resistant breast cancer, STING agonist monotherapy failed to active the STING signaling, due to the positive feedback of inactivated STING signaling and hyperactivated AKT1 strengthening the suppression of cGAS‐STING pathway by AKT1." (PMID 39023171, 2024). "In line with this, cGAS-dependent autophagy activation was recently reported to promote the growth and survival of highly chromosomally unstable BT-549 TNBC cells, but not of breast cancer lines with lower cytosolic genomic DNA burdens, by enabling the clearance of DNA from their cytosol." (PMID 36876871, 2023).
systemic lupus erythematosus (78 papers, 2017 to 2026). An autoimmune multi-organ disease typically associated with vasculopathy and autoantibody production. "cGAS deficiency enhances lupus-like symptoms and inflammatory pathology in a pristane-induced mouse model of lupus." (PMID 38396768, 2024). "Cells either lacking TOP1MT (EC 5.6.2.1) or expressing a pathogenic variant associated with lupus exhibit mtDNA release and activation of the cGAS–STING pathway." (PMID 37001140, 2023). "Contrary to STING-induced dendritic cell expansion in Fcgr2b-deficient mice, these data suggested that cGAS signaling inhibited the accumulation of pDCs and activated DCs in the pristane-induced lupus model." (PMID 36591278, 2022). "cGAS-dependent photosensitivity was recently shown in human TREX1- deficient cells from patients with lupus." (PMID 36091671, 2022). "A thorough study on the regulation of cGAS activity is deserved because the aberrant activation of cGAS causes severe autoimmune or autoinflammatory disorders, such as systemic lupus erythematosus (SLE) and Aicardi Goutières syndrome (AGS)." (PMID 28273161, 2017). "However, in vivo experiments showed the increased pDC expansion in cGAS-deficient mice, which hints to us to investigate the underlying mechanism of these findings that’s more complex in pristane-induced lupus than in vitro." (PMID 36591278, 2022). "Moreover, It has been showed that cGAS activation causes lupus-like autoimmune disorders in a TREX1 mutant mouse model." (PMID 33468161, 2021). "The persistent stimulation of cGAS-STING signaling has also recently been associated with systemic lupus erythematosus (SLE), a much more prevalent disease associated with IFN-I dysregulation." (PMID 33117352, 2020). "We further demonstrate that cGAS deletion protects mice from lupus-like symptoms induced by the TLR7 agonist imiquimod (IMQ)." (PMID 41851153, 2026). "The strongest data and genetic evidence support the development of cGAS-STING pathway inhibitors in systemic lupus erythematosus (SLE) and related auto-inflammatory syndromes." (PMID 39999142, 2025). "Further studies are needed to understand how the cGAS-STING pathway is involved in the pathogenesis of lupus." (PMID 40746538, 2025). "KAT2A has been reported to promote carcinogenesis in colorectal cancer by interacting with RNA-binding protein PTBP1 and to modulate cGAS through increasing expression and post-translational modification in systemic lupus erythematosus." (PMID 37047552, 2023). "This study aimed to identify the cGAS-mediated mechanisms contributing to lupus pathogenesis in PIL." (PMID 36591278, 2022). "Collectively, TANK inhibits the cGAS-dependent recognition of cytoplasmic DNA to prevent fatal DAH in the murine lupus model." (PMID 34819357, 2022). "In lupus patients, the chronic damage of different organs leads to the appearance of antiDNA antibodies, which suggest a contribution of the cGAS/STING pathway in this disease." (PMID 35406723, 2022). "IFIT3 can be targeted to block type I IFN and inflammatory cytokine synthesis by cGAS/STING pathway in lupus affected individuals." (PMID 34079550, 2021). "Notably, ZBP1 deficiency phenocopies blocking cGAS-STING pathway-mediated autoimmune pathology exacerbation in pristane-induced lupus-like mice, underscoring its context-dependent roles in lupus pathogenesis." (PMID 41773721, 2026). "Furthermore, multiple studies using murine models with lupus-like symptoms have demonstrated the critical role of cGAS-STING signaling in lupus pathogenesis." (PMID 40165656, 2025). "However, cGAS or STING deficiency resulted in exaggerated disease in the MRL/lpr mouse model and pristane-induced lupus model." (PMID 40746538, 2025). "Indeed, cGAS facilitates M1 pro-inflammatory macrophage polarization in various disease models, including myocarditis, lupus, and hepatitis B viral infection." (PMID 40507879, 2025). "Mutant TREX1-dsDNA―cGAS―STING―spontaneous lupus-like inflammatory." (PMID 41153813, 2025).